TNF (tumor necrosis factor)
Diseases named in the same sentence as TNF in open-access papers (continued):
Sharing a sentence is not in itself a finding about the gene and the disease.
rheumatic diseases (continued). "Apart from this, experimental studies have shown that hyperbaric oxygen therapy, etanercept (a tumor necrosis factor-alpha inhibitor used to treat rheumatic diseases), ketoprofen (a nonsteroidal antiinflammatory drug), and verapamil (a calcium channel blocker) reduced EF formation after laminectomy." (PMID 33984889, 2021). "The level of this cytokine is not routinely evaluated, and, as it influences plenty of cytokines, TNFα does not represent a highly specific marker for certain rheumatic diseases and could not be used for differential diagnosis." (PMID 33266394, 2020). "These facts indicate that the regulation of MMP and TNFα expression may be more diverse than presently known and that it still represents a relevant research target to elucidate the role of SFB in the pathophysiology of rheumatic diseases." (PMID 19622164, 2009). "The effect of rheumatism in the JWFSN-middle and JWFSN-high dose groups is particularly obvious, suggesting that the therapeutic effect of JWFSN on CIA rats may be through direct or indirect reduction of TNF-α, IFN-γ, and IL-1β expression and improve IL-4 and IL-10." (PMID 31929822, 2019). "This was a long-term, longitudinal cohort study of 50 patients with rheumatic diseases and negative baseline TB screening (TST: < 5 mm, negative T-SPOT.TB) treated with tumor necrosis factor inhibitors (TNFi) or other non-TNFi biologics." (PMID 32258853, 2020). "Each case was compared to two controls (with TJA and TNFα-blocker therapy, but without TJA infection) matched on age (±15 years), TJA localization, type of rheumatic disorder and disease duration (±15 years)." (PMID 20637100, 2010). "Prior to matching, the Yes-TNFα cohort was, on average, younger that the No-TNFα cohort (53.2 vs. 56.2 years), had a longer follow-up (1577.3 vs. 1418.8 days), and had lower prevalence of most CCI comorbidities with the exception of rheumatic disease (all SMD > 0.25)." (PMID 36902722, 2023).
Cirrhosis (233 papers, 2007 to 2025). A chronic disorder of the liver in which liver tissue becomes scarred and is partially replaced by regenerative nodules and fibrotic tissue resulting in loss of liver function. "Our previous study demonstrated that high levels of TNFα are associated with an increased risk of severe bacterial infections, which frequently trigger decompensating events in cirrhosis." (PMID 41004464, 2025). "Patients with cirrhosis have high systemic inflammation (TNFα, CRP, and IL-6) that is associated with poor outcomes." (PMID 39733165, 2024). "Signaling through the TNF-α/NF-kB axis has been linked to damage, fibrotic activity, and cirrhosis in the liver." (PMID 37122734, 2023). "LGG was reported as a safe and well-tolerated probiotic associated with a reduction in endotoxemia, TNF-α, and dysbiosis in patients with cirrhosis." (PMID 37761327, 2023). "The presence of bacterial DNA in the serum of patients with cirrhosis is associated with higher levels of cytokines such as TNF-α, IFN-γ, IL-12 and nitric oxide." (PMID 37822786, 2023). "The elevated serum and cardiac levels of cytokines like TNF-α suggest an underlying overactivation of cytokine/iNOS/cGMP pathway in cirrhosis." (PMID 36926084, 2022). "Cytokines such TNF-α, IL-10 and IL-17A are well described in association with chronic hepatitis, cirrhosis and HCC in combination with other proinflammation cytokines." (PMID 33435966, 2021). "So, it is noteworthy to explore the effects of the administration of a highly absorbed intestinal SIRT1 activator such as resveratrol on the coexisting TNFα-mediated intestinal and renal pathogenic changes as well as renal dysfunction in cirrhosis." (PMID 33513830, 2021). "This study explores the impacts of intestinal SIRT1 deficiency and TNFα-mediated intestinal abnormalities on the development of cirrhosis-related renal dysfunction." (PMID 33513830, 2021). "Despite no changes in food intake, the activation of ubiquitin–proteasome pathway through TNF-α/ NFκB signaling was the main reason for muscle loss in this animal model of cirrhosis induced by bile duct ligation." (PMID 31392488, 2019). "The TNF-α activity is increased in liver cirrhosis and generally thought to be associated with several known cirrhosis related complications such as hyperdynamic circulation, susceptibility to infection, and hepatic encephalopathy." (PMID 30123925, 2018). "Certain polymorphisms in TNF-α are also associated with higher risk of becoming chronic carriers of viral infection, progression to cirrhosis and HCC." (PMID 29033929, 2017). "Many other proinflammatory cytokines, including interleukin IL-1β, IL-18, and TNF-α have been associated with increased risk of progression to cirrhosis." (PMID 29033929, 2017). "Specifically, the TNF-α -238 A alleles were significantly more common in patients who suffered from chronic hepatitis than in those patients with cirrhosis." (PMID 23840511, 2013). "Owing to the location of the TNF-α gene within the HLA-region, the relation between HLA-haplotypes and TNF-α polymorphisms, including the influence on disease severity or chronic hepatitis evolution to cirrhosis, is possible." (PMID 23840511, 2013). "In the resultant model, the polymorphism of TNF-α at -238 was the only factor associated with cirrhosis." (PMID 23840511, 2013). "Studies have linked the development of cirrhosis-induced cardiac dysfunction with the activation of nuclear factor-κB and subsequent release of proinflammatory cytokines, including TNF-α and IL-1β, which up-regulate inducible nitric oxide synthase and subsequent nitric oxide release." (PMID 40738513, 2025). "Indeed, reduced expression of miR-29a and miR-29b has been associated with increased concentration of IL-6 and TNF-α and more advanced grades in patients with cirrhosis." (PMID 39125612, 2024).
Cirrhosis (continued). "Due to multiple hospitalizations with refractoriness to treatment with mesalazine, hematological side effects of azathioprine, side effects of corticosteroid use, and the risk of serious infection in patients with cirrhosis, we opted for the use of infliximab, an anti-TNF biological therapy." (PMID 39093785, 2024). "Thus, comprehensive longitudinal studies with a larger scale are needed to further explore TNF‐α gene polymorphism in different regional populations, considering all other cirrhosis‐related risk factors to validate these observations." (PMID 39315805, 2024). "CEACAM1 interacts with TNFα, playing a pathogenic role in cirrhosis-related hyperpermeability." (PMID 36741860, 2023). "Before DAA treatment, severe fibrosis or cirrhosis (F3/4) was associated with higher values of tumor necrosis factor-alpha (TNF-α) and genotypes transforming growth factor-beta-509 C/T_CC (TGF-β-509 C/T_CC), interleukine-10-1082 T/C_CC (IL-10-1082 T/C_CC), and IL-10-592 G/T_GT." (PMID 36674897, 2023). "Moreover, it was shown that TNF-α and IL-6 levels are elevated in cirrhosis, and these enhancements are associated with HC intensification." (PMID 32128089, 2019). "Kupffer cells trigger the release of factors such as TNF-α through NF-κB-mediated mechanisms which activates specific intracellular pathways through cascades, induce apoptosis, cause liver damage, and aggravate cirrhosis." (PMID 31533748, 2019). "Since higher plasma L-cystine/L-glutamate ratio was positively associated with TNF-alpha circulating levels in patients with advanced cirrhosis, our results may indicate an immune dysfunction state in these participants." (PMID 28878811, 2017). "Cirrhosis predisposes to recurrent episodes of subclinical translocation of intestinal bacteria and bacterial products resulting in increased levels of endotoxin (lipopolysaccharide [LPS]) and tumour necrosis factor-alpha (TNF-α)." (PMID 23446058, 2013). "A cytokine-leptin link hypothesis has also been suggested as a contributing factor to cirrhotic hyperleptinemia; presumably activated tumor necrosis factor-α (TNF-α) in cirrhosis can cause excessive release of leptin from adipose tissue." (PMID 17540037, 2007). "Our study demonstrated that rs1800896 AA and rs1799964 TT showed an interaction on reducing the risk of cirrhosis and a similar effect with rs1800896 AA and rs1799724 CT/TT genotype, suggesting IL‐10 and TNF‐α may have a synergistic effect in LC risk reduction." (PMID 39315805, 2024). "Indeed, serum levels of the pro-inflammatory cytokine interleukin-6 (IL-6), tumor necrosis factor-α (TNF-α), C-reactive protein, and lipopolysaccharide are elevated in patients with cirrhosis in parallel with the severity of disease, and are associated with poor outcomes." (PMID 35545763, 2022). "Fitting this, we measured increased plasma levels of both TGF-β and TNF-α in children with BA, and similar observations were made in an adult cirrhosis cohort." (PMID 40607400, 2025). "Inflammatory cytokines such as interleukin-6 (IL-6) and tumor necrosis factor-alpha (TNF-α) also play important roles in the progression of cirrhosis and are involved in the complications such as HE and HCC." (PMID 41149065, 2025). "Systemic Inflammation and Oxidative Stress: Chronic liver injury, such as MASH or cirrhosis, activates Kupffer cells and other immune cells, resulting in the release of pro-inflammatory cytokines (e.g., TNF-α, IL-6) and oxidative stress." (PMID 40001516, 2025). "Systemic inflammation has been well-recognized in liver cirrhosis, where knowns EC stimulants such as VEGF, TNF-α, IL-6, IL-8, and IL-1ra, are significantly elevated in the plasma of patients with cirrhosis." (PMID 39761260, 2025). "These cytokines fuel MASLD: TNF-α promoted liver lipid buildup, while IL-6 accelerated progression to cirrhosis or cancer." (PMID 41368575, 2025).
Cirrhosis (continued). "Chronic Inflammation and Oxidative Stress: Chronic liver disease, such as in MASH or cirrhosis, activates Kupffer cells and other immune cells, resulting in the release of pro-inflammatory cytokines (e.g., TNF-α, IL-6) and oxidative stress." (PMID 40001516, 2025). "Quantitative PCR revealed that FMT from HBV-cirrhosis patients upregulated the hepatic mRNA expression of inflammatory cytokines, including IL-6, TNF-α, and IL-18." (PMID 40642988, 2025). "A similar trend was observed for CD4+ T cells, where TNFα expression was downregulated after stimulation with IL-12 + IL-18 in compensated cirrhosis compared to healthy controls." (PMID 41028194, 2025). "With regard to CD4+ T cells, TNFα expression in decompensated cirrhosis patients was marginally elevated in comparison with compensated patients." (PMID 41028194, 2025). "Compared with patients with normal DAO levels, patients with decreased levels had higher levels of claudin 3, LPS, presepsin, TNF-a, and total bilirubin as well as more severe cirrhosis." (PMID 38543514, 2024). "Chronic exposure to elevated levels of circulating cytokines, such as tumor necrosis factor-alpha (TNF-α) and interleukin-6 (IL-6), plays a pivotal role in the inflammatory milieu that characterizes cirrhosis." (PMID 39859028, 2024). "SB reduced the serum TNF-α and IL-6 levels in experimental carbon tetrachloride-induced cirrhosis in rats and also reduced the level of CRP in one RCT with decompensated cirrhosis patients." (PMID 39203520, 2024). "In cirrhosis, endothelial activation and hemodynamic changes are related in part to elevated levels of TNF-α." (PMID 39337069, 2024). "In a cohort of 51 patients with a diagnosis of ACLF and decompensated cirrhosis, the degree of SI (levels of IL-10, IL-6, and TNF-α) determines the outcome." (PMID 39337069, 2024). "Infused albumin can also exhibit protective effects by binding to the cirrhosis-induced proinflammatory cytokines TNFα and IL6." (PMID 38551716, 2024). "Cirrhosis is a proinflammatory condition characterized by high serum levels of cytokines such as TNF-α, IL-6 and IL-1β, together with a decrease in anti-inflammatory molecules." (PMID 38337711, 2024). "Hedin et al21 found that in 18 patients with PSC-IBD with cirrhosis, treated with anti-TNF alpha inhibitors, the median baseline ALP and total bilirubin levels did not change significantly over 6- or 12- month follow-up period." (PMID 38206197, 2024). "TNF-α, IL-1β, IL-6, and NF-κB are key players in orchestrating inflammatory responses that can lead to liver damage, fibrosis, and cirrhosis." (PMID 38999918, 2024). "The blood levels of DAO were inversely correlated with blood levels of claudin 3, lipopolysaccharide (LPS), presepsin, TNF-α, and the severity of cirrhosis according to Child–Pugh scores." (PMID 38543514, 2024). "SB reduced the liver expression of the TNF-α and IL-6 genes in carbon tetrachloride-induced cirrhosis in rats." (PMID 39203520, 2024). "Utilization of Lactobacillus species; such as Lactobacillus plantarum and fructo-oligosaccharides, leads to a decrease in the production of primed TNF-α by peripheral blood mononuclear cells in individuals with cirrhosis." (PMID 39290562, 2024). "Similar to our study, the authors found that its level was higher in patients with cirrhosis than in the control group, higher in decompensated cirrhosis than in compensated cirrhosis, and correlated with the levels of LPS and TNF-alpha." (PMID 38543514, 2024). "Studies which stimulated monocytes or PBMCs from patients with cirrhosis or healthy controls with LPS ex vivo have indicated higher level of TNF-α, IL-1β and IL-6 production in the former." (PMID 38413535, 2024). "Next, we detected plasma inflammatory mediators (IL-6, IL-10, TNF-α, IL-8 and IL-12p70) in patients with cirrhosis and controls." (PMID 38413535, 2024). "In summary, increased TNF concentrations in GALT are crucial in the development of pathological BT in cirrhosis." (PMID 38191517, 2024).
Cirrhosis (continued). "Patients with cirrhosis had higher plasma levels of claudin 3, LPS, presepsin, and TNF-α, and lower plasma levels of DAO." (PMID 38543514, 2024). "The role of alcohol-induced cytokine TNF-α-associated inflammation in liver cirrhosis was established in a TNF-α gene knockdown mouse, which was resistant to alcoholic liver fibrosis/cirrhosis." (PMID 38665743, 2024). "Persistent alterations are observed only in chronic HCV patients with cirrhosis, displaying a distinct long-term pattern compared to IL-10, IL-22, TNFα, IFNγ, and IL-6." (PMID 39578604, 2024). "A higher trend of pro-inflammatory cytokines including IL-1α, IL-1β, IL-6, IL-8, IFN-γ and TNF-α was detected in the plasma from ACLF patients than that from cirrhosis patients, as well as the anti-inflammatory cytokines including IL-4, IL-10 and IL-13." (PMID 37380987, 2023). "In a rat cirrhosis model, GA prevented an increase in the levels of proinflammatory cytokines (IL-1α and TNFα) in the plasma and the depletion of the anti-inflammatory cytokine IL-4 resulting from chronic bile duct ligation." (PMID 36720896, 2023). "In particular, two landmark studies showed that anti-PD-1 treatment failed to reinvigorate CD8+ T cell tumor surveillance but paradoxically activated Cxcr6+ auto-aggressive CD8+TNF+PD-1+ T cells, which induce liver damage, cirrhosis, and HCC." (PMID 37586322, 2023). "An increase in IL-6 and TNF-α levels in patients with cirrhosis is involved in CRP production, suggesting that changes in CRP are linked to changes in these inflammatory cytokines." (PMID 36983211, 2023). "Here, patients with decompensated cirrhosis had significantly higher serum levels of Int-α2, Int-γ, TNF-α, IL-6, IL-8, IL-10, IL-23, and IL-33 compared to compensated patients, both in blood obtained from hepatic and jugular veins." (PMID 38077228, 2023). "This orchestration among HCV, NOXs, and TNF thus promotes chronic hepatitis, cirrhosis, and HCC development." (PMID 37827291, 2023). "Characteristics of included studies about polymorphisms in TNF-α and IFN-γ genes and cirrhosis of liver risk." (PMID 37122734, 2023). "Circulating levels of tumor necrosis factor (TNF)-alpha and interleukin (IL)-6 are increased in chronic HBV infection and are positively associated with disease progression (hepatitis B progression to cirrhosis or HCC)." (PMID 37312098, 2023). "The proportion of Treg and CD8 T cell-LAG3 (Exhausted CD8 T cell) enhanced, while the proportion of CD8 T cell-TNF (effector CD8 T cells) decreased from cirrhosis to HCC." (PMID 38116005, 2023). "Concordantly, preclinical studies demonstrate that ICB therapy in mice exacerbated NAFLD-HCC progression by aberrant re-activation of tissue-resident, auto-aggressive CD8+TNF+PD-1+ T cells that induce liver damage, cirrhosis, and finally tumorigenesis." (PMID 37586322, 2023). "Administration of 5 liters of fresh CM per week for 2 months (drinking) in patients of HCV, with mild to moderate parenchymal complications and mild cirrhosis, reduced TNF-α level." (PMID 35493477, 2022). "In the setting of decompensated cirrhosis, inflammatory cytokines (tumor necrosis factor-alpha (TNF-α) and interleukin-1b) upregulate inducible NO synthase (iNOS), and the NO produced as a result has a cardiotoxic effect." (PMID 36120195, 2022). "In cirrhosis, inflammatory cytokines TNFα, IL-1β and IL-6 are increased in cardiac tissue in cirrhotic animal models." (PMID 36926084, 2022). "Sequentially increasing numbers of M-MDSC with disease progression from compensated cirrhosis to AD/ACLF underlie the low TNF-α/IL-6 responses in AD/ACLF patients." (PMID 36926073, 2022). "Specifically, we observed TNFα depressing cardiac contractility with cirrhosis, and blockage of this cytokine using anti-TNFα antibody significantly improved systolic and relaxation velocities in cardiomyocytes from cirrhotic mice." (PMID 36926084, 2022).